GPI (glucose-6-phosphate isomerase)
Description:
Isomerase that catalyzes the conversion of alpha-D-glucose-6-phosphate to beta-D-fructose-6-phosphate, the second step in glycolysis, and the reverse reaction in gluconeogenesis, within the cytoplasm. Also shows C2-epimerase activity, interconverting D-glucose-6-phosphate (G6P) and D-mannose-6-phosphate (M6P) (By similarity). Also displays anomerase activity, interconverting alpha and beta-anomeric forms of G6P, D-fructose-6-phosphate and M6P (By similarity). In addition to its metabolic role, this enzyme functions extracellularly as a cytokine: acts as autocrine motility factor (AMF), a secreted angiogenic factor that enhances endothelial cell motility. Functions as neuroleukin, a neurotrophic factor supporting the survival of spinal and sensory neurons. Released by lectin-stimulated T-cells to induce immunoglobulin secretion.
Synonyms: AMF; NLK; PGI; PHI; SA-36; CNSHA4; GNPI; SA36
Tractability: Small molecule: a structure with a bound ligand is known; it has a high-quality binding pocket. Antibody: UniProt places it where antibodies can reach, with high confidence; its Gene Ontology location is reachable by antibodies, with high confidence. PROTAC: UniProt records ubiquitination sites on it; ubiquitination databases record sites on it; its protein half-life has been measured.
Target class: Isomerase; Enzyme
Gene: Protein-coding gene on chromosome 19 (34,359,480 to 34,402,413, forward strand). Ensembl gene ENSG00000105220.
Subcellular location: Cytoplasm; Secreted
Subcellular location (Human Protein Atlas): Cytosol; Plasma membrane; Predicted to be secreted
Pathways (Reactome):
Metabolism: Gluconeogenesis; Glycolysis
Immune System: Neutrophil degranulation
Gene Ontology:
Molecular function: glucose-6-phosphate isomerase activity; protein binding; ubiquitin protein ligase binding; glucose-6-phosphate 1-epimerase activity; monosaccharide binding; racemase and epimerase activity, acting on carbohydrates and derivatives; carbohydrate derivative binding; isomerase activity
Biological process: glucose 6-phosphate metabolic process; positive regulation of endothelial cell migration; positive regulation of immunoglobulin production; canonical glycolysis; carbohydrate metabolic process; gluconeogenesis; glycolytic process; hemostasis; humoral immune response; carbohydrate derivative metabolic process; fructose 6-phosphate metabolic process; learning or memory; negative regulation of apoptotic process; response to cadmium ion; response to estradiol; response to immobilization stress; response to muscle stretch; response to progesterone; response to testosterone
Cellular component: cytoplasm; extracellular exosome; extracellular region; membrane; cytosol; ficolin-1-rich granule lumen; secretory granule lumen; ciliary membrane; plasma membrane
Genetic constraint (gnomAD): Loss-of-function variants: 44 observed, 65.69 expected, observed/expected ratio (o/e) 0.67, 90% interval 0.52 to 0.86. The upper end of that interval is the gene's LOEUF score, 0.86, which puts it in group 3 of 6, group 1 being the genes least tolerant of losing a copy. Missense variants: 570 observed, 680.67 expected, observed/expected ratio (o/e) 0.84, 90% interval 0.78 to 0.9. Synonymous variants: 260 observed, 262.34 expected, observed/expected ratio (o/e) 0.99, 90% interval 0.89 to 1.1.
Homologues: Orthologues: chimpanzee GPI (99% identical), macaque GPI (98% identical), pig GPI (93% identical), dog UBA2 (93% identical), guinea pig GPI (93% identical), mouse Gpi1 (89% identical), rat Gpi (88% identical), zebrafish gpia (78% identical), zebrafish gpib (78% identical), tropical clawed frog gpi (75% identical), Drosophila melanogaster Pgi (68% identical), Caenorhabditis elegans gpi-1 (67% identical), and 1 more.
Diseases named in the same sentence as GPI in open-access papers:
GPI is named in the same sentence as 140 diseases in open-access papers, as found by Europe PMC text mining. Sharing a sentence is not in itself a finding about the gene and the disease. The quoted sentences say what the papers report.
Arthritis (95 papers, 2005 to 2026). Inflammation of a joint. "Arthritis in K/BxN mice is provoked by pathogenic autoantibodies to glucose-6-phosphate isomerase (G6PI), which is a ubiquitously expressed enzyme that is present in cells, in the circulation and on articular cartilage." (PMID 41683705, 2026). "In this study, we analyzed the association of the incidence and severity of glucose-6-phosphate isomerase (G6PI)-induced arthritis with age in two different mouse strains." (PMID 34429153, 2021). "This activates GPI-reactive B cells, which leads to the production of anti-GPI autoantibodies, causing arthritis." (PMID 30858306, 2019). "A single injection of anti-GPI antibody caused prolonged and more severe arthritis in B cell-deficient KBN mice." (PMID 29495570, 2018). "The K/BxN mouse is a spontaneous model of arthritis driven by T cell receptor transgenic CD4+ T cells from the KRN strain that are activated by glucose-6-phosphate isomerase (GPI) peptides presented by the H-2g7 allele from the NOD strain." (PMID 30233578, 2018). "The KBN mouse is a spontaneous model of arthritis driven by T cell receptor transgenic CD4+ T cells from the KRN strain that are activated by glucose-6-phosphate isomerase (GPI) peptides presented by the H-2g7 allele from the NOD strain." (PMID 30233578, 2018). "For instance, in the K/BxN mouse model, arthritis is induced by pathogenic autoantibodies directed against glucose-6-phosphate isomerase." (PMID 26302382, 2015). "High titers of anti-GPI antibodies are present in arthritis-resistant C57BL/6 mice (H-2b), although the T cells of these animals exhibited weak GPI responses compared with arthritis-susceptible DBA/1 mice (H-2q)." (PMID 18534002, 2008). "In mouse arthritis models, FcγRIII deficient hosts exhibit resistance to collagen type II induced arthritis and anti-glucose-6-phosphate isomerase (GPI) antibody induced arthritis, suggesting that FcγRIII is indispensible in autoantibody dependent arthritis." (PMID 16277670, 2005). "To confirm that the arthritis resistance was intrinsic to T cells, we transferred thymocytes from SH3gl1 deficient or wild-type littermate mice into TCRβ knockout mice before the induction of glucose-6-phosphate isomerase (GPI) induced arthritis." (PMID 33504785, 2021). "The development of arthritis in K/BxN serum-transferred mice, a model in which autoantibodies against glucose-6-phosphate isomerase play an important role, is suppressed by the deficiency of factor B, C3, C5 or C5a, but not by C1q or MBP-A, suggesting the involvement of the AP in the pathogenesis." (PMID 26404464, 2015). "Indeed, aldolase and α-enolase have been already described as autoantigens in RA; and in the K/BxN mouse model, arthritis is induced by pathogenic autoAb directed against another glycolytic enzyme, the glucose-6-phosphate isomerase." (PMID 19284558, 2009). "This suggests that anti-GPI antibody positivity might predispose individuals with the FCGR3A-158V/V genotype to arthritis." (PMID 16277670, 2005). "Moreover, FcγRIII deficient mice were resistant to anti-GPI antibody induced arthritis." (PMID 16277670, 2005). "The STA model relies on the injection of serum collected from arthritic K/BxN mice, which contains anti-glucose-6-phosphate isomerase immune complexes that induce transient arthritis in recipient mice by activating the innate immune system." (PMID 40755771, 2025). "Later, GPI was identified as an auto-antigen in RA patients, and immunization with GPI protein was found to induce arthritis in DBA/1 mice with a T cell and B cell dependent pattern." (PMID 38547647, 2024). "Population distribution of scRNA-seq data of hind paw joint cells isolated at the indicated time points of glucose-6-phosphate isomerase (GPI)-induced arthritis were determined." (PMID 37024468, 2023). "Serum from K/BxN mice contains autoantibodies against glucose-6-phosphate isomerase that induce destructive arthritis mediated by T and B cells." (PMID 36420272, 2022).
Arthritis (continued). "For example, an isoquinoline series was identified that was efficacious in a glucose-6-phosphate isomerase (GPI)-induced mouse arthritis model." (PMID 36467083, 2022). "Meanwhile, to confirm the observed tolerance in the BQ.Col2266E mice was antigen-specific, we immunized the mice with another self-antigen glucose 6-phosphate isomerase (GPI) peptides, and they were fully susceptible to GPI-induced arthritis." (PMID 35963953, 2022). "A more relevant model of RA is the KRN/I-Ag7 (or K/BxN) mouse model of arthritis, mediated by a polyclonal T-cell dependent autoantibody response to a ubiquitous cytoplasmic glucose-6-phosphate isomerase (GPI)." (PMID 33451011, 2021). "Although many murine models of arthritis have inflammation effector features, the injection of K/BxN mice serum containing antibodies against glucose-6-phosphate isomerase (G6PI) mainly induce inflammatory arthritis by initiating innate immune system." (PMID 34950033, 2021). "The K/BxN serum-transfer arthritis model is induced by injecting anti-glucose-6-phosphate isomerase (anti-GPI)-positive serum from K/BxN mice into commonly used mouse strains, leading to pathological changes resembling human RA." (PMID 31947680, 2020). "In an in vivo study, CTLA-4Ig suppressed the generation of large amounts of TNF-α and IFN-γ by splenocytes from DBA/1 mice with glucose-6-phosphate isomerase-induced arthritis." (PMID 33322156, 2020). "The K/BxN serum transfer arthritis model is induced by injecting anti-glucose-6-phosphate isomerase (anti-GPI)-positive serum from K/BxN mice into commonly used mouse strains." (PMID 33114670, 2020). "In our studies, we examined the glucose-6-phosphate-isomerase (GPI)-serum-induced experimental RA to monitor the temporal dynamics of the effector phase of arthritic joint disease." (PMID 32514887, 2020). "GRA458T (GRdim) knock-in mice with attenuated GR dimerization, but intact monomer activity, were found refractory in arthritis models of antigen-induced arthritis, glucose-6 phosphate isomerase (G6PI)-induced arthritis and STIA." (PMID 31681333, 2019). "We found that mice that received P2rx7−/−.K/BxN T cells developed worse arthritis and had increased anti-GPI auto-Abs, indicating amplified autoimmunity compared to mice that received WT K/BxN T cells." (PMID 30949163, 2019). "Naïve mice injected with KBN serum, affinity-purified anti-GPI antibodies, or a combination of two or more anti-GPI mAbs induced arthritis." (PMID 29495570, 2018). "The K/BxN mice develop a severe and destructive form of arthritis, which is associated with high titers of antibodies recognizing glucose-6-phosphate isomerase (GPI), making it a valuable serum transfer model of arthritis." (PMID 30149545, 2018). "In fact, anti-IL-17A and anti-IL-17 receptor A aptamers inhibited the progression of experimental autoimmune encephalomyelitis (EAE), glucose-6-phosphate isomerase (GPI)-induced arthritis, collagen-induced arthritis, and osteoarthritis in mice." (PMID 27827561, 2017). "Transfer of K/BxN mouse serum or affinity-purified anti-GPI antibodies induces arthritis in most strains of mice." (PMID 28235016, 2017). "We and others have reported that arthritis can be induced simply by passively transferring anti-GPI autoantibodies or serum containing anti-GPI autoantibodies into wild-type mice." (PMID 28810929, 2017). "Anti-GPI autoantibodies appear to be the primary drivers of disease, because the transfer of K/BxN serum, or even K/BxN-derived anti-GPI monoclonal antibodies, is sufficient to induce arthritis in other mouse strains (see later)." (PMID 28666464, 2017). "Although CD4 T cells were dispensable to arthritis induced by the injection of anti-GPI antibody (K/BxN serum transfer arthritis), autoreactive KRN CD4 T cells were required for the initiation of arthritis in K/BxN mice." (PMID 28753982, 2017).
Arthritis (continued). "Here we present quantitative measurements of bone degradation characterised by the cortical bone profile using glucose-6-phosphate isomerase (G6PI) induced arthritis." (PMID 28290525, 2017). "The in vivo systems used were LPS- and SEA-induced cytokine production in the mouse, antigen-induced arthritis in the rat, glucose-6-phosphate isomerase-induced arthritis in the mouse and delayed-type hypersensitivity reaction in the mouse." (PMID 27340371, 2016). "For example, the glucose 6-phosphate isomerase (GPI) specific T-cell transgenic K/BxN mouse develops attenuated arthritis in germ-free conditions but develops more severe arthritis when inoculated with commensal bacteria." (PMID 25861466, 2015). "We herein analyzed the roles of PADI4 in inflammatory arthritis using a glucose-6-phosphate isomerase (GPI)-induced arthritis (GIA) model in Padi4 knockout (KO) mice." (PMID 26293116, 2015). "K/BxN mice develop arthritis at 1 month of age and generate spontaneous responses against the ubiquitous autoantigen glucose-6-phosphate-isomerase (GPI)." (PMID 25793195, 2015). "Arthritis severity, serum anti-GPI antibody titers, and IL-6 concentrations were significantly reduced in Padi4 KO mice." (PMID 26293116, 2015). "Recombinant human glucose-6-phosphate isomerase (rhGPI)-induced arthritis (GIA) is an established and immunologically characterized model of RA18." (PMID 26293116, 2015). "Glucose-6-phosphate isomerase (GPI)-induced arthritis is a closer model of human rheumatoid arthritis based on its association with CD4+ T cells and cytokines such as TNF-α and IL-6 than CIA." (PMID 23251456, 2012). "Both C5a receptor and FcγRIII have been reported to play co-dominant roles in the CII antibody induced arthritis (CAIA) and glucose-6-phosphate isomerase serum-induced arthritis." (PMID 22906101, 2012). "We here examined the relationship between the efficacy of MTX and the expression of SLC19A1 in glucose 6-phosphate isomerase (GPI)-induced arthritis." (PMID 22546471, 2012). "Recently, nilotinib was tested in a glucose-6-phosphate-isomerase-induced arthritis mouse model and found to significantly prevent paw inflammation – to a greater extent than imatinib." (PMID 21909252, 2011). "We chose to examine the effect of B cell depletion in glucose-6-phosphate isomerase (G6PI)-induced arthritis." (PMID 21931827, 2011). "We studied the clinical and immunological effects of B cell depletion in glucose-6-phosphate isomerase-induced arthritis." (PMID 21931827, 2011). "Signalling of radioisotope 18F labelled Fluorodeoxyglucose (18F-FDG) injected in mice with glucose-6-phosphate isomerase (G6PI)-induced arthritis was analysed by PET/CT." (PMID 21047399, 2010). "In GPI-induced arthritis, both TNFα and IL-6 antagonists have protective effects, and these cytokines play important roles in the induction of arthritis in collaboration with autoantibodies (anti-GPI antibodies)." (PMID 19660107, 2009). "The present study was designed to examine the effects and immunological change of action of altered peptide ligands (APLs) on glucose-6-phosphate isomerase (GPI) peptide-induced arthritis." (PMID 19900268, 2009). "Schubert and colleagues reported that continuous injections of human TNF receptor (TNFR) p75-IgG-Fc fusion protein (Etanercept) from days 0 to 9 completely protected against the development of arthritis in glucose-6-phosphate isomerase (GPI)-induced arthritis." (PMID 19660107, 2009). "In K/B × N mice, anti-GPI antibodies solely induce arthritis through activation of complements and Fcγ receptors." (PMID 18534002, 2008). "Recent studies identified co-localization of IgG and C3 on the articular surface of joints in GPI-induced arthritis on day 14, and production of anti-GPI antibodies was most vigorous on day 8 (Tanaka and coworkers, unpublished data)." (PMID 18534002, 2008).
Arthritis (continued). "In the K/BxN model, arthritis is mediated by anti-GPI antibodies and was demonstrated to depend on FcRγ and components of the alternative complement pathway." (PMID 18710572, 2008). "Glucose-6-phosphate isomerase (GPI)-induced arthritis, a murine model of RA, is induced by immunisation with recombinant human (rh) GPI of DBA/1 mice." (PMID 18992137, 2008). "Arthritis induced by immunisation with glucose-6-phosphate isomerase (GPI) in DBA/1 mice was proven to be T helper (Th) 17 dependent." (PMID 18992137, 2008). "To explore the relationship between functional polymorphisms in FcγRs (FCGR3A-158V/F and FCGR2A-131H/R) and arthritis in individuals positive for anti-GPI antibodies, we evaluated these individuals with respect to FCGR genotype." (PMID 16277670, 2005). "In K/B×N mice, polyclonal or two monoclonal anti-GPI antibodies induced arthritis in several strains of mice." (PMID 16277670, 2005). "In human RA, anti-GPI antibodies have frequently been detected in patients with aggressive forms of arthritis, and their levels correlated significantly with extra-articular manifestations such as rheumatoid nodules, rheumatoid vasculitis and Felty's syndrome." (PMID 16277670, 2005). "Antibodies specific for glucose-6-phosphate isomerase (G6PI) from T-cell receptor transgenic K/BxN mice are known to induce arthritis in mice, and immunization of DBA/1 mice with G6PI led to acute arthritis without permanent deformation of their joints." (PMID 16277685, 2005). "In contrast to PD-1/PD-L1 and CTLA-4, where agonistic approaches have therapeutic benefit, blockade of ICOS or its ligand (ICOSL) reduces disease severity in murine models of rheumatoid arthritis, such as the glucose-6-phosphate isomerase (GPI)-induced arthritis model." (PMID 41007749, 2025). "Similarly, the prophylactic use of APL-12 derived from human glucose 6 phosphate isomerase (hGPI 325–339) improves the severity of arthritis via Treg induction in the GPI-induced arthritis mouse model." (PMID 36901730, 2023). "We next assessed whether the protective activities of MCTR3 were retained in a model of adaptive immune system-driven arthritis using the glucose-6-phosphate isomerase peptide driven model of inflammatory arthritis." (PMID 35430453, 2022). "Furthermore, the role of IFNγ in animal models of RA remains controversial as it is shown to be protective in the collagen-induced model but required for arthritis development when induced by glucose-6-phosphate isomerase." (PMID 34478449, 2021). "In vivo studies on several animal models, including collagen and glucose-6-phosphate isomerase-induced arthritis induced arthritis in mice and antigen-induced arthritis in rats, showed that AMAP102 exhibited anti-arthritic effects and reduced inflammatory pain responses." (PMID 33498477, 2021). "Antibodies against glucose-6-phosphate isomerase (anti-GPI), distinctively pathogenic in the K/BxN T cell receptor transgenic mouse arthritis model, were first described in 64% of RA patients but not in controls." (PMID 34054878, 2021). "To determine whether anti-RhoB Ig could inhibit autoantibody production, we employed the established K/BxN murine model of arthritis that is mediated by high titers of anti-GPI autoantibodies." (PMID 28882929, 2017). "In this arthritis model the level of anti-GPI Ig is correlated tightly with disease progression." (PMID 28882929, 2017). "Interestingly, SFB colonization has been shown to exacerbate arthritis in K/BxN mice, an autoimmune model of arthritis arising from T cell auto-reactivity to the glycolytic enzyme glucose-6-phosphate isomerase." (PMID 28645307, 2017). "In addition to the spontaneous arthritis, the most evident pathological abnormality is the presence of anti-glucose-6-phosphate isomerase (GPI) antibody production in K/BxN mice." (PMID 26903711, 2016).